TNF (tumor necrosis factor)
Diseases named in the same sentence as TNF in open-access papers (continued):
Sharing a sentence is not in itself a finding about the gene and the disease.
endotoxemia (continued). "Endotoxemia studies in dogs showed that these beneficial effects of choline treatment might be related with inhibition of TNF-α synthesis, prevention of hepato-renal injury, and attenuation of the changes of serum butrylcholinesterase and paraoxonase-1 activities." (PMID 27646125, 2016). "The results of this study demonstrate that the suppression of cardiac vagal activity and sympathetic predominance during endotoxemia are predominantly linked to the anti-inflammatory IL-1ra response to IL-1ß activation rather than to the pro-inflammatory response by IL-6 or TNF-α." (PMID 25893426, 2015). "Therefore, we hypothesized that ATF3 may modulate the expression of IL-6 and TNF-α in the early and later stages of endotoxemia." (PMID 24062788, 2013). "The mechanism may involve suppression of alcohol-induced endotoxemia thereby downregulating endotoxin-induced activation of NF-κB and further going downstream the signalling cascade including TNF-α, NO and ROS and by enhancing the antioxidant profile of the chronically alcohol-fed host." (PMID 21673994, 2011). "However, mTORC1-S6K activation occurred equally well in mice deficient for TNF-α receptor knockout, suggesting TNF-α signaling does not play a significant role in mTORC1-S6K activation in endotoxemia." (PMID 21200439, 2010). "Thus, preservation of Eh Cys/CySS by SAA supplementation may be involved in decreased IL-1β and TNF-α levels during endotoxemia." (PMID 19325908, 2009). "Experimental findings regarding the roles of ET-1, TNF-a and intestinal endotoxemia in the development of IPVD in the pulmonary microvasculature may contribute towards understanding the physiopathology of HPS in humans and allow the use of new treatments in the future." (PMID 20011928, 2009). "Intriguingly, in an LPS-induced endotoxemia model, induction of ACOD1 was found to reduce TNF production, which also deviates from our findings in an inhaled exposure model." (PMID 39351225, 2024). "Insulin has anti-inflammatory effects, and the application of insulin can reduce pro-inflammatory mediators, especially TNFα and IL6, in animal models of endotoxemia." (PMID 37063831, 2023). "Among fatty acids, ethyl palmitate (compound 42) reduced plasma levels of tumor necrosis factor-α (TNF-α) and IL-6, decreased NF-κB expression in liver and lung tissues, and ameliorated histopathological changes in an LPS-induced endotoxemia rat model." (PMID 36139047, 2022). "We found that F-652 injection significantly improved the survival rates and reduced pro-inflammatory cytokines (IL-6, TNF-a, IL-1β, MCP-1) in LPS-induced endotoxemia mice." (PMID 36123595, 2022). "In turn, the CD14−CD163+ monocytes, which resemble human intermediate monocytes and release the highest amount of TNF upon ex vivo stimulation, followed the kinetics of WBC and significantly decreased the expression of SLA-DR during endotoxemia." (PMID 35566768, 2022). "Earlier studies demonstrated that metformin reduced mortality in a mouse model of lethal endotoxemia by inhibiting HMGB1 release; inhibition of NF-κB-induced TNF-α activation and AMPK activation were the mechanisms contributing to the protective effects." (PMID 35156512, 2022). "We have previously demonstrated, via measurements of splenic and whole blood levels of TNFα and splenic levels of IL-1α, that splenic pFUS modulates the systemic signaling of CAP and NF-KB in a rat model of endotoxemia." (PMID 36478877, 2022). "This indicated that KCF18 alleviated the mRNA expression levels of the inflammatory cytokines TNF-α, IL-1β, IL-6, and MCP-1 in an endotoxemia mouse model with liver injury." (PMID 35370629, 2022). "Microbial imbalance and endotoxemia are able to promote the expression of pro-inflammatory cytokines, such as IL6, TNF-α, IL-1, and plasminogen activator inhibitor-1 in a TLR-4 dependent manner." (PMID 33536239, 2021).
endotoxemia (continued). "Vagus nerve stimulation increases the concentration of acetylcholine in the spleen, inhibits the production of TNF-α by macrophages, and reduces serum TNF-α levels during endotoxemia." (PMID 34717724, 2021). "In the LPS administration endotoxemia model, both MA and EA at ST36 decreased the number of c-Fos cells in brain tissues and TNF-α in serum and decreased TNF-α mRNA expression and TNF-α signal intensity in the spleen." (PMID 35095910, 2021). "Baicalein decreased the generation of TNF-α or IL-6 and inhibited the activation of NF-κB or ERK1/2 in mice with LPS-induced lethal endotoxemia." (PMID 33995078, 2021). "For animals resuscitated with PolyHSA, serum TNF-α and IL-1β levels were significantly lower compared to animals resuscitated with HSA 24 h after LPS induced endotoxemia." (PMID 34035380, 2021). "In general, many additional pro-inflammatory mediators controlled by NF-κB p65 are known (e.g., TNF-α, IL-1β, IL-6 and MCP-1) and their contribution to the observed effects of Aqp9 deletion on the survival to endotoxemia can be anticipated." (PMID 33670755, 2021). "These and other previous studies showed that VIP downregulates TNFα expression in LPS-treated RAW264.7 cells and activated microglia, and in vivo in models of nerve injury and endotoxemia." (PMID 34025407, 2021). "Compared to those in the sham group, the plasma levels of LPS, IL6 and TNFα were found to be significantly reduced in the RYGB group, indicating that endotoxemia and systemic inflammation were prominently alleviated by RYGB." (PMID 34290269, 2021). "Both compounds exhibit a moderate activity in LPS-induced endotoxemia model and CIA, compared to that of a potent pan-PDE4 inhibitor – rolipram, which most strongly inhibited CIA progression and TNF-α plasma levels in LPS-induced endotoxemia." (PMID 31899535, 2020). "We examined serum concentrations of IL-1β, IL-6, TNF-α, and IL-10 to investigate the effect of BAFF antibody on systemic inflammation in endotoxemia." (PMID 33324396, 2020). "In a rat model of inflammation, TNF showed a similar temporal abundance pattern in skin ISF and serum during endotoxemia, although the concentration was 5–10 times higher in serum." (PMID 33224151, 2020). "Using structural equation models, we also tested if the relationship between endotoxemia and cardiometabolic complications was mediated by the latent (unobserved) variable inflammation inferred from the observed biomarkers CRP, TNF-α and IL-6." (PMID 33299020, 2020). "In children with NAFLD, the serum endotoxin, TNF-α, IL-6, and PAI-1 levels were higher suggesting that endotoxemia can contribute to the progression of NAFLD." (PMID 33505393, 2020). "Only IgA21 significantly inhibited HFD-induced endotoxemia and significantly reduced serum LBP and TNF-a (P < 0.04 vs. HFD)." (PMID 31178854, 2019). "For example, PGE2 is a negative regulator for LPS-induced production of TNF-α in Epac/PKA-, of IFN-β in Epac/PI3K/Akt-dependent signaling in activated macrophages and during endotoxemia." (PMID 30981278, 2019). "For marker of endotoxemia, serum endotoxin and LBP were measured using TNF-α and IL-6 levels as indices of systemic inflammation." (PMID 31178854, 2019). "In a murine endotoxemia model, AWRK6 offered satisfactory protection efficiency against endotoxemia death, and the serum levels of LPS, IL-1β, IL-6, and TNF-α were found to be attenuated using ELISA." (PMID 29463000, 2018). "In the lung, chronic alcohol pre-exposure enhanced endotoxemia-induced acute lung injury (ALI), which was prevented by blocking systemic TNF-α with etanercept." (PMID 28812994, 2017). "Mice treated with AMD3100 displayed impaired health status and showed enhanced serum levels of TNF alpha, IFN gamma and NO levels in endotoxemia." (PMID 27716214, 2016).
endotoxemia (continued). "A body of animal and clinical trials have shown that DEX decreases cytokine (TNF-α, IL-6) secretion after endotoxin injection and that DEX reduced the mortality rate in endotoxemia-induced shock rat models in a dose-dependent manner." (PMID 26171113, 2015). "In line with this notion, the deacetylation-mediated interaction of HMGB1 and SIRT1 in mice was sufficiently potent to robustly protect against endotoxemia in response to LPS challenge by inhibiting the secretion of HMGB1 and cytokines such as TNF-α and IL-6." (PMID 26522327, 2015). "AICAR or compound C treatment decreased ALT, AST, and TNF levels in serum, reduced CD68 expression and MPO activity in liver tissue of mice with endotoxemia." (PMID 24475189, 2014). "Macrophages secrete TNF-α, and TNF-α elicits MCP-1 release; one can expect a positive feedback loop generated by these cytokines that will aggravate the inflammation of endotoxemia." (PMID 24062788, 2013). "In previous studies, our group showed that endotoxemia plays an important role in the initiation and aggravation of ALD through the enhancement of proinflammatory cytokines, including IL-6, IL-8, and TNF-α." (PMID 24385684, 2013). "To explain the mechanism involved in the plasmid-induced attenuation of MAP drop in LPS-stimulated rats, we determined the gene expression of liver IL-6 and TNF-α and plasma concentration of AVP and NO, key mediators in endotoxemia." (PMID 23137350, 2012). "Since plasmids was found to decrease in vitro production of TNF-α and IL-6 by LPS-stimulated macrophage cell line and these cytokines play a key role in the inflammatory process, we evaluate if low doses of plasmid could have a beneficial effect in vivo in an endotoxemia model." (PMID 23137350, 2012). "It is well known that a progressive release of cytokines and other inflammatory mediators, including TNF-α, IL-1β, IL-12p40, IFN-γ and NO, involve the trigger of multiple organ dysfunction during endotoxemia." (PMID 23285207, 2012). "These peptides also inhibited LPS-induced TNF-α release in human PBMCs and induced lower levels of TNF-α in the serum in a subclinical endotoxemia mouse model." (PMID 21660935, 2011). "Clinical trials have shown that GTS-21 intervention in patients with endotoxemia does not lead to substantial differences in the serum levels of the proinflammatory cytokines TNF-α and IL-6 compared to those in controls." (PMID 40337863, 2025). "During the development of endotoxemia, LPSs bind to toll-like receptor 4 (TLR4) and increase the concentration of inflammatory markers such as IL-1α, IL-6, INF-γ, and TNF-α, and consequently systemic chronic intestinal inflammation may develop." (PMID 39193369, 2024). "In comparison with the control, 5 in 7 ATB+DSS mice demonstrated normal stool consistency with systemic inflammation (alanine transaminase, endotoxemia, TNF-α, and IL-6), implying the leaky gut without an overt diarrhea." (PMID 39546435, 2024). "In Candida-Bil Nep, probiotics improved survival rate, serum IL-6 (not TNF-α and IL-10), endotoxemia, and bacteremia with increased fecal butyric acid." (PMID 36969207, 2023). "In CLP alone, the Ezh2 inhibitor attenuated kidney damage (serum creatinine) and serum cytokines (TNF-α, IL-6, and IL-10) but not cell-free DNA, endotoxemia, and bacteremia." (PMID 37239864, 2023). "↑ Veillonellaceae, endotoxemia, and inflammation (IL-6, TNF-α, IL-2, and IL-13) in cirrhotic patients with HE vs. without HE.↑ Enterobacteriaceae, Alcaligeneceae, and Fusobacteriaceae and ↓ Ruminococcaceae and Lachnospiraceae compared with controls." (PMID 37367929, 2023). "Additionally, IL-1β and TNFα stimulate the release of HMGB1, a late mediator of endotoxemia, and exaggerate the inflammatory damage." (PMID 36776867, 2023). "Our study demonstrates that, in the absence of Gal3, the early LPS-induced peak of circulating TNF-α and IL-6 is significantly attenuated, thus further supporting the deleterious effect of Gal3 under conditions of endotoxemia." (PMID 35163089, 2022).
endotoxemia (continued). "Moreover, in vivo study showed that acute administration of quercetin (1, 10, 50, or 100 mg/kg injected intraperitoneally) decreased the lethality rate and circulating levels of TNF-α and IL-1β in C57BL/6J mice with endotoxemia induced by LPS." (PMID 36588685, 2022). "As TNF-α can modulate endotoxin-induced upregulation of IL-1β and IL-6, we thus conjectured that the SEM18 peptide can decrease the endotoxemia-induced upregulation of IL-1β and IL-6 in plasma and lung tissues as well as the endotoxemia-induced bindings of IL-1β/IL-1R and IL-6/IL-6R in lung tissues." (PMID 35337084, 2022). "The application of the CRG/Ech complex and CRG, one day before the injection of LPS, promoted a 1.5–2-fold reduction in TNF-α production in mouse blood cells compared with the group of animals that did not receive samples before the induction of endotoxemia." (PMID 36233004, 2022). "Collectively, these data display that the SEM18 peptide significantly inhibited TNF-α and IL-1β, but not IL-6, in endotoxemia-treated mouse lung tissues." (PMID 35337084, 2022). "In endotoxemia mice, CPE could decrease IL-6, MCP-1, TNF-α, and PGE2 levels in the serum after a single therapeutic administration, showing a definitely anti-inflammatory activity." (PMID 36238556, 2022). "Acetylcholine can inhibit the production of TNFα, IL (interleukin)-1β, IL-6, and IL-18, but not IL-10, during lethal endotoxemia in rats." (PMID 34948222, 2021). "For animals resuscitated with HSA and PolyHSA, serum TNF-α and IL-1β levels were significantly lower at 6 and 24 h after LPS induced endotoxemia compared to animals that received no fluid resuscitation." (PMID 34035380, 2021). "In the present study, the PLA data indicated that KCF18 could simultaneously inhibit more than 70% binding of TNF-α to TNFR1, more than 80% binding of IL-1β to IL-1R, and approximately 70% binding of IL-6 to IL-6R in the liver tissues of mice with endotoxemia." (PMID 34065201, 2021). "Moreover, it is unclear if the modulations of TLR4 and TNF-α in both the guts and livers of EtOH + Fen-treated mice are a direct effect of Fen on TLR4 signaling, are from reductions in systemic endotoxemia, or both." (PMID 33815111, 2021). "In addition, both probiotics also attenuated liver enzyme (alanine transaminase), oxidative injury (reduced MDA and increased GSH), serum cytokines (TNF-α, IL-6, and IL-10), and gut leakage (FITC-dextran assay and endotoxemia)." (PMID 35010955, 2021). "Endotoxemia-induced lung edema, neutrophil accumulation, nuclear translocation of NF-κB and production of proinflammatory cytokines (IL-1β and TNF-α) in lung neutrophils are reduced in transgenic mice lacking the catalytic subunit of PI3Kγ." (PMID 33821232, 2021). "As expected, compared with the NCD group, the HFD group displayed a significant increase in serum LPS, TNF-α, and IL-6 levels, which was reversed by PEW supplementation, suggesting that PEW might prevent HFD-induced endotoxemia and systemic inflammation." (PMID 32256675, 2020). "SM administrated at a dose 50 mg/kg to mice with LPS-induced non-lethal endotoxemia decreased the TNF-α level by 2.1-fold, but the differences were statistically insignificant." (PMID 33114200, 2020). "Increased levels of wet-to-dry weight ratio; BAL fluid total protein; and IL-6, TNF-α, MIP-2 and VEGF protein production were observed in mice with endotoxemia treated with high-tidal-volume compared with the other MV treatment groups and the nonventilated control mice." (PMID 32353952, 2020). "In addition, the serum levels of TNF-α and IL-6 in TEPP-46-pretreated mice were significantly decreased compared to those in endotoxemia mice." (PMID 33542713, 2020). "Because IL-18 regulates the synthesis of TNF-α, IL-1β, IL-8 and MIP-1α, removal of IL-18 may have a beneficial effect in lethal endotoxemia in naive mice." (PMID 32503314, 2020).
endotoxemia (continued). "Our second objective was to test, using structural equation models, if the relationship between endotoxemia and cardiometabolic complications was mediated by the latent (unobserved) variable inflammation inferred from the observed biomarkers CRP, TNF-α and IL-6." (PMID 33299020, 2020). "During experimental endotoxemia, PCSK–9 knock-out mice produced significantly lower levels of pro-inflammatory cytokines, including interleukin-6 (IL–6) and tumor necrosis factor–α (TNF–α)." (PMID 32796672, 2020). "Some AMPs have a specifically high affinity to lipopolysaccharides (LPS, endotoxins) from Gram-negative bacteria and are able to suppress an LPS-induced release of tumor necrosis factor alpha (TNF-α) and could protect mice from lethal endotoxemia." (PMID 31683553, 2019). "In itself, the careful physical placement of the cervical vagus nerve on the electrodes in this study did not significantly change serum TNF levels in endotoxemia." (PMID 31551672, 2019). "During endotoxemia, LPS-induced toll-like receptor-4 (TLR-4) activation promotes expressions of inflammatory cytokines including tumor necrosis factor-α (TNF-α), interleukins (IL-1β and IL-6) through transcription of nuclear factor-κB (NF-κB), which is a crucial regulator of immune system." (PMID 28852469, 2017). "In contrast, LPS-induced endotoxemia in mice was shown to be protected by MCP-1 administration, which increases plasma IL-10 levels, and to be exacerbated by anti-MCP-1 antibody administration, which increases the peak TNF-α and IL-12 levels." (PMID 28272428, 2017). "Induction of colonic TNF-α mRNA by endotoxemia was, in accord with observations in spleen, not further increased by changes in ambient temperature (data not shown)." (PMID 28706520, 2017). "Unlike its protective activity in CBA mice, bLf failed to confer protection against endotoxemia and E. coli bacteremia in C3H/HeCr mice due to its inability to ameliorate the elicitation of TNF-α and IFNγ, and to prevent IL-6 decrease." (PMID 28257033, 2017). "When, GBZ was instead injected only 1 h after the endotoxin to match the kinetics of TNF-α production, survival in the LPS/GBZ cohort increased to 67%, demonstrating that GBZ can conserve its protective effect during ongoing endotoxemia." (PMID 28659918, 2017). "The translocated LPS are detected by CD14 and toll-like receptor 4 (TLR4), which causes the release of pro-inflammatory cytokines such as tumor necrosis factor alpha (TNFα), interferon alpha (IFNα), interferon-gamma (INFγ) and interleukins (IL1β or IL6), which can eventually result in endotoxemia." (PMID 27924137, 2016). "Nanomechanical changes induced by TNF-α and thrombin, respectively, were identical to those seen after LPS exposure, suggesting that glycocalyx deterioration is not confined to endotoxemia, but probably occurs across the whole spectrum of critical illness." (PMID 24278345, 2013). "Most importantly, acute administration of quercetin reduces the lethality rate and circulating levels of TNF-α and IL-1β in C57BL/6J mice with endotoxemia induced by LPS, whereas chronic dietary supplementation with quercetin shows no inhibitory effect on serum TNF-α and IL-1β levels." (PMID 24260470, 2013). "It was found that dexmedetomidine at the doses of 10 and 20 μg/kg decreased CLP-induced pulmonary inflammation and mortality, reduced production of IL-6 and TNF-α in plasma and BALF of septic rats, and suppressed TLR4/MyD88 expression and NF-κB activation in lung of endotoxemia rats induced by CLP." (PMID 23690665, 2013). "Experimental observations indicate that IL-22 application in murine endotoxemia fails to significantly affect production of the pro-inflammatory cytokines TNFα, IL-6, and IFNγ analyzed in the early phase (up to 8 h after onset of endotoxemia) of the syndrome." (PMID 23382730, 2013).